TESK2 (testis associated actin remodelling kinase 2)
Description:
Dual specificity protein kinase activity catalyzing autophosphorylation and phosphorylation of exogenous substrates on both serine/threonine and tyrosine residues. Phosphorylates cofilin at 'Ser-3'. May play an important role in spermatogenesis.
Tractability: Small molecule: a high-quality ligand is known; it belongs to a druggable protein family. PROTAC: it is named in the literature on targeted protein degradation; ubiquitination databases record sites on it; a small molecule that binds it is known.
Target class: Protein Kinase; TKL protein kinase group; Kinase; Enzyme
Gene: Protein-coding gene on chromosome 1 (45,343,877 to 45,491,203, reverse strand). Ensembl gene ENSG00000070759.
Subcellular location: Nucleus
Subcellular location (Human Protein Atlas): Nucleoplasm
Gene Ontology:
Molecular function: protein binding; protein kinase activity; protein serine/threonine kinase activity; ATP binding; protein serine kinase activity; protein serine/threonine/tyrosine kinase activity; protein tyrosine kinase activity
Biological process: actin cytoskeleton organization; focal adhesion assembly; protein phosphorylation; spermatogenesis
Cellular component: nucleoplasm; cytoplasm; nucleus
Genetic constraint (gnomAD): Loss-of-function variants: 38 observed, 57.61 expected, observed/expected ratio (o/e) 0.66, 90% interval 0.51 to 0.87. The upper end of that interval is the gene's LOEUF score, 0.87, which puts it in group 3 of 6, group 1 being the genes least tolerant of losing a copy. Missense variants: 627 observed, 746.25 expected, observed/expected ratio (o/e) 0.84, 90% interval 0.79 to 0.9. Synonymous variants: 244 observed, 277.87 expected, observed/expected ratio (o/e) 0.88, 90% interval 0.79 to 0.98.
Homologues: Orthologues: macaque TESK2 (98% identical), dog TESK2 (91% identical), rabbit TESK2 (90% identical), rat Tesk2 (90% identical), chimpanzee TESK2 (89% identical), pig TESK2 (89% identical), mouse Tesk2 (87% identical), guinea pig TESK2 (83% identical), tropical clawed frog tesk2 (70% identical), zebrafish tesk2 (63% identical). Paralogues in human: TESK1 (47% identical), LIMK1 (25% identical), LIMK2 (24% identical), MAP3K9 (23% identical), LRRK2 (21% identical), MAP3K21 (21% identical), MAP3K10 (21% identical), MAP3K11 (20% identical), MAP3K20 (20% identical), RIPK1 (19% identical), TNNI3K (19% identical), MAP3K12 (18% identical), and 11 more.
Diseases named in the same sentence as TESK2 in open-access papers:
TESK2 is named in the same sentence as 5 diseases in open-access papers, as found by Europe PMC text mining. Sharing a sentence is not in itself a finding about the gene and the disease. The quoted sentences say what the papers report.
breast carcinoma (1 paper, 2015). "A kinase previously not linked to breast cancer subtypes, TESK2, also showed a trend for more frequently harboring an HFI SNP (rs17853159) in TNBC compared to ER+cancers (16% vs 3%, P-unadjusted = 0.06)." (PMID 26420498, 2015).
cblC (1 paper, 2022). "The presence of the PRDX1 mutation and the potential clinical consequences of TESK2 silencing in epi-cblC cases suggest that it should be considered as a distinct entity." (PMID 35440018, 2022). "We unraveled the methylome architecture of the CCDC163P–MMACHC CpG island (CpG:33) and the TESK2 CpG island (CpG:51) of 17 epi-cblC cases." (PMID 35440018, 2022). "We unraveled the methylome architecture of the CCDC163P/MMACHC CpG island (CpG:33) and the TESK2 CpG island (CpG:51) by studying the epigenome-wide DNA methylation profile of the 17 epi-cblC cases." (PMID 35440018, 2022). "The RNA-seq data analysis showed that the readthrough transcription of PRDX1 was prolongated through the MMACHC/CCDC163P bidirectional promoter and the TESK2 promoter in fibroblasts of epi-cblC patients." (PMID 35440018, 2022).
lung adenocarcinoma (1 paper, 2022). A carcinoma that arises from the lung and is characterized by the presence of malignant glandular epithelial cells. "The low expression of TESK2 is associated with poor survival of patients with lung adenocarcinoma and premetastatic stage in human lung-to-brain metastasis." (PMID 35440018, 2022).
cancer (2 papers, 2015 to 2022). A tumor composed of atypical neoplastic, often pleomorphic cells that invade other tissues. "In conclusion, our results show that epi-cblC should be distinguished from cblC, with potential consequences on spermatogenesis and cancer risk produced by TESK2 silencing." (PMID 35440018, 2022). "TESK2 is a dual specificity protein kinase that phosphorylates both serine/threonine and tyrosine residues and has not previously been implicated in cancer but plays a role in spermatogenesis." (PMID 26420498, 2015).
TESK2 also shares sentences with these, for which no sentence is quoted: rheumatoid arthritis (1 paper).